KIT (KIT proto-oncogene, receptor tyrosine kinase)
Diseases named in the same sentence as KIT in open-access papers (continued):
Sharing a sentence is not in itself a finding about the gene and the disease.
melanoma (continued). "KIT mutations in melanoma correlate with specific clinicopathological features and are candidates for KIT targeted therapies but has limited evidence of efficacy." (PMID 37483495, 2023). "Only a small number of mucosal melanoma patients which harbor mutations in BRAF or KIT benefit from targeted therapy." (PMID 37831226, 2023). "Unfortunately, KIT inhibitors like imatinib have limited efficacy in melanoma cases with the D816V mutation." (PMID 37504268, 2023). "KIT mutations are found in 2–8% of melanoma cases and are more common in acral melanomas and melanomas associated with low CSD." (PMID 37958863, 2023). "These triple-negative melanomas most commonly contain KIT (10.9–24.4%), GNAQ (18.6%), TYRP1 mutations." (PMID 37239381, 2023). "Approximately 70% of KIT mutations in melanoma are missense mutations (well described in reference)." (PMID 36844227, 2023). "Mutations in KIT, a known tumour marker and proto-oncogene, accounts for about 3% of all melanomas, but are more prevalent in melanomas on chronically sun-damaged skin." (PMID 36612301, 2023). "This real‐world study was conducted to assess the association of BRAF, NRAS, or KIT mutations with outcome in melanoma receiving adjuvant anti‐PD‐1 monotherapy." (PMID 37403699, 2023). "Though the role of KIT alternations has been established in mastocytosis and melanoma, mutations show heterogeneous distribution through the gene in both diseases." (PMID 37372988, 2023). "In our panel, KIT mutations are distributed across all 20 tumor types, with the three most common being soft tissue sarcomas (15.3%), melanomas (9.8%), and osteosarcomas (8.9%) (total N = 885)." (PMID 36658200, 2023). "KIT/c-KIT gene activation is oncogenic and associated with several tumor types, such as melanoma, lung cancer, and gastrointestinal stromal cancers." (PMID 37509254, 2023). "As KIT mutations are one of the most frequently mutated genes in melanomas, it is a potential target for advanced melanoma treatment." (PMID 37239381, 2023). "Activating mutations in the KIT gene have been identified in melanoma and can lead to the constant activation of the RAS-RAF-MEK-ERK-MAPK pathway." (PMID 37504268, 2023). "For instance, KIT mutations, one of the major mutations observed in mucosal melanoma (~25%), are related with the upregulation of glucose metabolism in mucosal melanoma cells." (PMID 37444561, 2023). "KIT mutation (19.1–23.1%) was the most frequently found driver mutation in mucosal melanomas followed by NF1 (7.8–16.4%), RAS (6.2–17.9%), and BRAF (3.1–16.4%) mutations." (PMID 37239381, 2023). "While imatinib improves melanoma patients with KIT alterations, subsequent KIT mutations result in imatinib resistance." (PMID 35954441, 2022). "KIT mutations are reported in 3% of melanomas and are more common in acral and mucosal sites as well as sun-exposed skin melanomas." (PMID 36064728, 2022). "BRAF and NRAS are the most frequently affected oncogenes in acral melanomas but at a lower frequency compared to sun-exposed melanomas, whereas KIT mutations are more common in acral melanomas." (PMID 35197475, 2022). "The roles of the novel mutations in exon 13 of the c-KIT gene in the tolerance to imatinib in GISTs or melanoma remain uncertain." (PMID 35720122, 2022). "The combination of KIT inhibitors with PD‐1 inhibitors is a new trend for melanoma with c‐KIT gene mutations (NCT05274438)." (PMID 36254250, 2022). "KIT mutations are present in 3% to 9.5% of melanoma patients; mutations are present in approximately 23% of acral melanomas and 15.6% of mucosal melanomas." (PMID 35954441, 2022).
melanoma (continued). "KIT mutations are identified in 3% of all melanomas, specifically in about 35% of acral and mucosal melanomas." (PMID 36232957, 2022). "Imatinib is the most wel- studied KIT inhibitor and is currently recommended for the treatment of KIT-mutated melanoma." (PMID 35640549, 2022). "It has been shown that Imatinib mesylate treatment of advanced melanoma yielded significant clinical responses in patients with KIT gene mutations." (PMID 36686701, 2022). "There is an immediate advantage to outlining patients for KIT mutations in melanoma patients before participating in clinical trials associated with targeted agents based on these correlations." (PMID 36551688, 2022). "Mutations in the oncogene c-KIT are more frequent in melanomas arising within skin with chronic sun-induced damage than in nonchronic sun-damaged skin." (PMID 35804995, 2022). "Preclinical data have highlighted a completely different mutational background in melanoma V600K with the overexpression of c-KIT, the inhibition of multiple proapoptotic pathways and a reduced dependence on the ERK/MAPK pathway." (PMID 35160279, 2022). "A phase II study is recruiting patients with c‐KIT‐mutated melanoma for second‐line therapy with regorafenib (NCT02501551)." (PMID 36254250, 2022). "The findings indicate a possible role for FER amplification in driving the MAPK pathway, similar to KIT, another receptor tyrosine kinase that can be amplified or mutated in acral and mucosal melanoma, frequently also in conjunction with NF1 mutations." (PMID 35706047, 2022). "In melanoma, new markers are continuously exposed through bioinformatics technologies, and multiple markers including IL27, CXCL8, THBS1, and KIT have been identified to be associated with melanoma metastasis and treatment outcomes." (PMID 36438905, 2022). "Within MM, KIT mutations are much more common in melanomas affecting the vulvovaginal tract compared with sinonasal melanomas." (PMID 35640549, 2022). "For example, acral and mucosal melanomas have fewer BRAF mutations but more frequent KIT mutations, amplifications of CCND1, CDK4, and MDM2, and deletion of SPRED1." (PMID 35706047, 2022). "Activating mutations in KIT can be found in up to 36% of AM and 39% of MM, which is considerably more than in melanomas arising from chronically sun damaged skin (1%-7%) or intermittent sun-damaged skin (rare to never)." (PMID 35640549, 2022). "These drugs are mainly administered in CML, but some trials demonstrated the efficacy of KIT mutated melanoma, including MMs." (PMID 34065883, 2021). "We also suggested that KIT mutations defined aggressiveness in melanoma, which is consistent with TCGA data." (PMID 33648909, 2021). "C‐kit inhibitors have demonstrated modest benefit in clinical trials of patients with KIT‐mutated melanoma, but have been less effective in unselected cohorts of mucosal melanoma patients." (PMID 33724703, 2021). "The frequencies of these genetic aberrations also differ depending on the tissue of origin of these melanomas, for instance, KIT mutations are more common in mucosal melanomas." (PMID 34359736, 2021). "It is worth noting that 28% of high-CSD, 36% of acral, and 39% of mucosal melanomas were found to have KIT copy number gains or mutations." (PMID 35008286, 2021). "TERT promoter mutations and CDKN2A are also frequently found in these melanomas, and KIT mutations are found in a subset of cases." (PMID 34571969, 2021). "Mutations also occur in the proto-oncogene tyrosine-protein kinase KIT (c-KIT) in 1–7% of melanomas, being specifically associated to acral lentiginous melanoma and mucosal melanoma or chronic sun damage." (PMID 34207514, 2021). "KIT encodes the receptor tyrosine kinase c-KIT that is involved in various signaling pathways in melanoma including melanocyte development, MAPK/ERK signaling, PI3K/AKT signaling, and MITF upregulation." (PMID 35008286, 2021).
melanoma (continued). "Several other c-KIT inhibitors, including sunitinib, dasatinib, pexidartinib, sorafenib, ponatinib, and nilotinib, were tested and showed variable activity in c-KIT mutated melanoma as well." (PMID 33918490, 2021). "In this study based on the prevalence of KIT mutations in melanoma, a large patient set confirmed the high occurrence of such mutations in acral and mucosal melanomas." (PMID 33648909, 2021). "Among them, reported trauma and KIT mutations have been more frequently associated with subungual melanomas than with AMs occurring in other locations." (PMID 34213090, 2021). "The majority of c-KIT mutations are found in mucosal and acral melanomas, as well as in melanomas arising from skin." (PMID 34441278, 2021). "Studies targeting BRAF, NRAS and KIT showed KIT as the most common mutated gene in urogenital tract melanomas, with a mutation frequency higher than 25%." (PMID 33525348, 2021). "Melanoma Triple-WT subgroup show the highest median KIT protein abundance with enrichment of KIT mutations, focal amplifications and complex structural rearrangements." (PMID 33918490, 2021). "Patients whose mucosal melanomas harbored a KIT mutation had one of the strongest associations with a favorable DCB, although it did not meet our threshold for statistical significance (71% vs. 28%, adjusted p‐value 0.16)." (PMID 33724703, 2021). "The most common mutation in mucosal melanoma is in the KIT gene with a range of mutations and gene amplification observed." (PMID 33724703, 2021). "For example, a previous study found that an acquired activating N-RAS mutation was associated with c-KIT inhibitor resistance in c-KIT-mutant melanoma." (PMID 33807778, 2021). "Imatinib is less effective in treating melanoma with activating mutations in the c-KIT kinase domains compared to those with activating mutations in the juxtamembrane (JM) domain (encoded in exon 11), which is known to have an autoinhibitory function." (PMID 33807778, 2021). "An S628N substitution in exon 13 was identified as a gain-of-function mutation, and melanoma carrying this c-KIT mutation demonstrated susceptibility to imatinib treatment." (PMID 33807778, 2021). "The functional characteristics of these mutations are clinically significant as KIT inhibitors are effective in melanomas, but with a much lower degree of clinical response (10–30%) compared with GIST (>70%)." (PMID 34203771, 2021). "In phase II clinical trials, the KIT inhibitor imatinib has been evaluated in patients with mucosal melanoma harboring KIT mutations, with an overall disease control rate of ~50%." (PMID 35048028, 2021). "The initial KRAS-mutated melanoma of patient 1 (left) showed only minor differences to the KIT-mutated and NRAS-mutated part of the tumor (middle, right)." (PMID 34072863, 2021). "Further investigation of the KIT mutation status and toceranib therapy in canine malignant melanoma will need to be undertaken." (PMID 33827546, 2021). "Other selective KIT-inhibitors (with lower IC50) that demonstrated some kind of activity in KIT-mutated melanoma are nilotinib, avapritinib and masitinib (NCT01280565)." (PMID 35008245, 2021). "Unfortunately, because of the relative rarity of c-KIT mutations (1–7%), the availability of targeted therapy to treat this type of melanoma is limited." (PMID 34441278, 2021). "The association between pigment cell anomalies and c-KIT mutation is well established, including certain types of melanomas, such as acro lentiginous melanoma." (PMID 34064058, 2021). "From the available NGS data of our cases, copy number variants affecting CDKN2A and KIT are frequently seen in mucosal melanomas." (PMID 34571863, 2021). "The cBio Cancer Genomics Portal (cBioPortal) is one of the most comprehensive public databases and allowed us to analyze the BRAF, KRAS, and KIT mutation status from 14 different studies focused on melanomas." (PMID 34769348, 2021).
melanoma (continued). "KIT encoded by KIT harboring a mutation c.1725_1733del is a potential therapeutic target for toceranib in canine malignant melanoma." (PMID 33827546, 2021). "The presence of c-KIT mutations has shown to be associated with worse survival as compared with wild-type melanomas." (PMID 34441278, 2021). "In conclusion, we showed here the so far largest study on KIT mutations in melanoma patients for a Spanish population." (PMID 33648909, 2021). "The average somatic mutation rate of c-KIT-mutant melanomas is even higher (30 mutations per Mb, n = 3, p = 0.02) compared to severely sun-damaged (SSD) skin (21 per Mb) and non-SSD skin (3.8 per Mb)." (PMID 33807778, 2021). "Mutations and amplification of the KIT oncogene are more frequent in melanomas arising in the skin with chronic sun damage, acral sites, or mucosal melanomas." (PMID 34447613, 2021). "KIT mutations have been observed in varying frequencies in melanomas arising at different primary sites." (PMID 34102999, 2021). "High KIT gene expression in BRAFV600K-mutated melanomas has been reported, concurrent with the significant downregulation of KIT-targeting miRNAs, including miR-222." (PMID 34123788, 2021). "Candidate driver events in Triple-WT melanomas include KIT mutations/amplifications and co-amplified RTKs such as PDGFRA and KDR (VEGFR2)." (PMID 33918490, 2021). "Treatment approaches with tyrosine kinase inhibitors (TKIs) targeting KIT mutations have been conducted in several clinical trials in relapsed and refractory melanomas." (PMID 34831002, 2021). "KIT encodes a receptor tyrosine kinase protein named mast/stem cell growth factor receptor (SCFR), which stimulates both the MAPK and PI3K-Akt pathways; thus, in melanoma, mutations in KIT lead to deregulated growth and survival of cells." (PMID 34884858, 2021). "The first trial investigating the targeted therapy of KIT mutations was reported in 2011 and included a total of 51 melanoma patients who received imatinib." (PMID 34831002, 2021). "A trend was observed associating mutations in KIT gene with vascular invasion and thicker melanomas." (PMID 33648909, 2021). "Patients who achieved a CR or a PR had KIT mutations in exons 11 and 13 in acral or mucosal melanomas." (PMID 34831002, 2021). "In our study, moderate or strong cytoplasmic KIT expression was detected in 6 of the 19 cases (31.6%), and KIT mutations were observed in 21% (4/19) of the mucosal melanomas of female genital tract." (PMID 34102999, 2021). "KIT gene expression has been correlated with activating mutations, which indicates the role of KIT in tumorigenesis in melanoma." (PMID 34447613, 2021). "KIT mutations were detected in 12 (6.2%) melanoma patients, with the most frequent mutations being L576P, N822K, and R634Q." (PMID 34454530, 2021). "A high KIT mutational rate was particularly reported in mucosal melanomas, but differences between mucosal and SKMs were invalidated in Caucasians." (PMID 34769348, 2021). "The difference in the distribution of KIT mutations in different melanoma subtypes was statistically significant (p<0.001)." (PMID 33648909, 2021). "The first trial aiming at evaluating sunitinib in melanoma patients with mutations, amplifications, or overexpression of KIT showed benefit and proposed further studies." (PMID 33918490, 2021). "This is an open-labelled single-arm clinical trial of the use of imatinib mesylate and pembrolizumab combination therapy for Japanese metastatic KIT-mutated melanoma patients who failed ICIs treatment." (PMID 34889232, 2021). "Our results differ from previous studies reporting a higher prevalence of KIT mutations in CSD melanomas." (PMID 33648909, 2021). "While KIT mutation and/or amplification were reported to be adverse prognostic marker in melanomas in the Asian population, KIT mutation correlates with better PFS for vulvar melanomas in our series." (PMID 34571863, 2021).
melanoma (continued). "Our results suggested that KIT mutations in melanoma tumors are unrelated to nevus proneness or chronic sun damage, but their presence is associated with aggressive melanomas showing ulceration, vascular invasiveness, and increased Breslow thickness." (PMID 33648909, 2021). "For the present meta-analysis, correlations to patients with BRAF, NRAS, and KIT mutations, clinical-pathological characteristics and risk factors correlated to the development of melanoma were grouped together." (PMID 31274706, 2020). "In the past decade accumulating molecular epidemiologic evidence indicated that KIT mutation also occurs in melanoma." (PMID 31848942, 2020). "Melanoma patients benefit from the off-label use of KIT inhibitors, imatinib and nilotinib, only after stratification based on their KIT mutation status." (PMID 33256089, 2020). "To determine the endogenous constitutive activity of each KIT mutation, we assessed the phosphorylated levels of KIT in each melanoma cell line by Western blot." (PMID 32344828, 2020). "Many studies have reported the incidence of KIT mutations and focal amplifications in melanoma and their association with clinicopathologic characteristics." (PMID 32344828, 2020). "Several studies have implicated the efficiency of imatinib in mucosal melanoma, and several ongoing trials focus on the effect of KIT inhibition." (PMID 33585548, 2020). "Thirteen of all studies analysed reported the melanoma localization and the presence of KIT gene mutations." (PMID 31274706, 2020). "The majority of c-KIT mutations are found in mucosal and acral melanomas, as well as in melanomas arising from skin with CSD." (PMID 32429485, 2020). "A small subset of melanoma patients have DNA alterations in KIT that manifest as point mutations and amplifications in less than 7% of cutaneous melanoma patients, and in approximately 40% of mucosal and acral melanoma patients." (PMID 33256089, 2020). "It has been classically estimated that around 2–8% of melanomas that arise within cumulative sun-damaged skin exhibit KIT gene mutations." (PMID 32825562, 2020). "Approximately 70% of KIT mutations identified in melanoma and leading to constitutive activation of kinase activity are localized in exon 11 (L576P) or exon 13 (K642E)." (PMID 32850962, 2020). "As reported by Lassam and Bickford, and by Montone and colleagues, an interesting observation regarding KIT in melanomas is the decrease (or even the loss) of KIT expression along with the progression of the neoplastic disease." (PMID 33321993, 2020). "There is therefore a clear need for combination therapies to improve the prognosis for patients with KIT-mutated melanoma." (PMID 32344828, 2020). "STAT3 is a critical point of convergence downstream of several hyperactive tyrosine kinase receptors that are either mutated or amplified in melanoma, such as KIT, ERBB4, EPH, FGFR, EGFR and PDGRFA, among others." (PMID 33396645, 2020). "The activity of imatinib mesylate in KIT mutated melanoma patients was explored through three single arm phase II trials." (PMID 32850962, 2020). "Funnel plot analysis demonstrates no bias in published studies which analyse mutations in BRAF, NRAS, and KIT genes for patients with melanoma, according to their sex, melanoma subtype, localization of melanoma, chronic solar exposure, and ulceration." (PMID 31274706, 2020). "In comparison, in the double wild type mucosal melanoma cohort the KIT mutation frequency was similar the cutaneous variants (7/17, 41.2%)." (PMID 31848942, 2020). "KIT-mutated melanoma, which represent around 22% of triple-wild-type melanoma, respond poorly to targeted therapies and immunotherapies." (PMID 32344828, 2020). "Comparison of the mutation profile in CTCs and in the resected primary melanoma showed some heterogeneity, particularly for the KIT gene." (PMID 32260071, 2020). "To confirm the involvement of MAPK in regulating BIM in KIT-mutated melanoma, we used the MEK inhibitor trametinib." (PMID 32344828, 2020).